KCNJ10 (potassium inwardly rectifying channel subfamily J member 10)
Diseases named in the same sentence as KCNJ10 in open-access papers (continued):
Sharing a sentence is not in itself a finding about the gene and the disease.
Seizure (12 papers, 2008 to 2025). A seizure is an intermittent abnormality of nervous system physiology characterized by a transient occurrence of signs and/or symptoms due to abnormal excessive or synchronous neuronal activity in the brain. "Seizure-susceptible DBA/2 mice carry the T262A mutation in the Kcnj10 gene and show impaired Kir4.1 channel activity and reduced glutamate clearance by astrocytes in the hippocampus." (PMID 30356026, 2018). "Seizure susceptibility has been linked to mutations in four selected candidate genes; Pex19, Kcnj10, Pigm, and Cabc1." (PMID 22952935, 2012).
glioblastoma (11 papers, 2011 to 2025). The most malignant astrocytic tumor (WHO grade IV). "The IL-1β expression is significantly upregulated in glioblastoma and negatively correlated with the expression levels of KCNJ10, suggesting that KCNJ10 may promote inflammation in the TME." (PMID 36199579, 2022). "Glioblastoma studies included E5 (KCNJ10, KCNN3), E21 (KCNAB2), E26 (KCNE2, KCNJ13), E27 (KCNE4, KCNMB2-AS1), E31 (KCNJ10), E50 (KCND3), and E51 (KCNIP1, KCNJ16, KCNN2)." (PMID 40867621, 2025).
autism spectrum disorder (10 papers, 2016 to 2024). A spectrum of developmental disorders that includes autism, and Asperger syndrome. "In contrast, heterozygous gain-of-function mutations (R18Q, V84M, and R348H) in KCNJ10 caused autism spectrum disorders with spastic seizures and intellectual disability." (PMID 33424762, 2020). "Although no information on the structure-activity relationship for Kir4.1 channel stimulators is available, gain-of-function mutations of the KCNJ10 gene (e.g., R18Q in N-terminus and V84M in TM1 region) reported in patients with autism spectrum disorders may give hints for new drug discovery." (PMID 33424762, 2020).
Intellectual disability (10 papers, 2012 to 2024). "In the current study, potassium inwardly rectifying channel subfamily J member 10 (KCNJ10) mutation was detected in one patient who presented with drop attacks, movement disorder, and intellectual disability." (PMID 37628333, 2023). "KCNJ10 mutations contribute to ASD with seizures and intellectual disability." (PMID 36817099, 2022).
temporal lobe epilepsy (10 papers, 2012 to 2024). A localization-related (focal) form of epilepsy characterized by recurrent seizures that arise from foci within the temporal lobe, most commonly from its mesial aspect. "In addition, several SNPs of KCNJ10 have been shown to be associated with temporal lobe epilepsy (TLE) with febrile seizures." (PMID 23922547, 2013). "We investigated Kir4.1 (Kcnj10) and IL-1β mRNA expression in the temporal cortex in a rat model of temporal lobe epilepsy 24 h and 1 week after induction of status epilepticus (SE), using real-time PCR and western blot analysis." (PMID 23270518, 2012).
amyotrophic lateral sclerosis (9 papers, 2017 to 2024). Amyotrophic lateral sclerosis (ALS) is a neurodegenerative disease characterized by progressive muscular paralysis reflecting degeneration of motor neurons in the primary motor cortex, corticospinal tracts, brainstem and spinal cord. "Crucially, Kcnj10 levels appear reduced in astrocytes generated from amyotrophic lateral sclerosis (ALS) patients, providing a potential explanation for the muscle weakness seen in this disease (see also Section 7.1)." (PMID 32183137, 2020).
Hypokalemia (9 papers, 2021 to 2026). An abnormally decreased potassium concentration in the blood. "Whole-exome sequencing (WES) excluded pathogenic variants in renal tubulopathy genes including SLC12A3 (Gitelman syndrome), SLC12A1, CLCNKB, BSND, KCNJ1, MAGED2 (Bartter syndrome), and CASR, CLCNKA, KCNJ10 (hypokalemia-associated genes)." (PMID 40893942, 2025). "The mutation in the KCNJ10 gene is responsible for defective potassium transport in those locations, resulting in seizures, hearing loss, and hypokalemia." (PMID 39381482, 2024). "The importance of the Kir4.1/Kir5.1 channel was further established by the identification of KCNJ10 and KCNJ16 mutations in patients with hypokalemia and hypomagnesemia, mimicking Gitelman syndrome." (PMID 35554666, 2022). "On the other hand, mice in which Kcnj10 was knocked out in the principal cell develop hypokalemia when fed a low‐K+ diet or with thiazide treatment because of an inability to downregulate ENaC and ROMK activity in the knockout mouse." (PMID 34665521, 2021).
Pendred syndrome (7 papers, 2004 to 2024). Pendred syndrome (PDS) is a clinically variable genetic disorder characterized by bilateral sensorineural hearing loss and euthyroid goiter. "Accordingly, it is known that free radical stress-mediated loss of specific protein expression (i.e., Kcnj10) in stria vascularis contributes to hearing loss in Pendred syndrome mouse model." (PMID 25789325, 2015). "The gene KCNJ10 encodes an inwardly rectifying potassium (K+) channel, namely the Kir4.1 channel, expressed in a wide variety of tissues but most importantly in the case of Pendred syndrome, in the cochlear stria vascularis which maintains the endocochlear potential and K + homeostasis." (PMID 23965030, 2013). "It should be noted that autosomal recessive SNHL with EVA and/or Pendred syndrome also can be diagnosed with one pathogenic variant in SLC26A4 and one in either FOXI1 or KCNJ10." (PMID 36675424, 2023). "Two other genes have been described to cause Pendred syndrome, accounting for less than 2% of affected individuals: FOXI1 encoding Forkhead box protein I1 and KCNJ10 encoding the adenosine triphosphate-sensitive potassium channel." (PMID 36529647, 2022). "The present study investigates whether variants in KCNJ10 and FOXI1 in combination with heterozygosity for SLC26A4 mutations are likely to be associated with the disease phenotype seen in Pendred syndrome/EVA patients (who already have one mutation in the SLC26A4 gene)." (PMID 23965030, 2013). "Two genes, KCNJ10 and FOXI1, have been investigated for their role in the PDS disease spectrum and it has been proposed that digenic mutations in both SLC26A4 and either FOXI1 or KCNJ10 may cause Pendred syndrome." (PMID 23965030, 2013).
astrocytomas (6 papers, 2009 to 2023). "In addition, Kir4.1(KCNJ10) expression is low in astrocytomas and oligodendrogliomas." (PMID 36703789, 2022).
Hyperglycemia (5 papers, 2020 to 2026). An increased concentration of glucose in the blood. "However, astrocyte markers, including CD44, KCNJ10, TGFBR2, GFAP, and S100β, were upregulated under hyperglycaemia, as shown by both NGS transcriptomic analysis and immunostaining." (PMID 41419458, 2025). "Interestingly, astrocyte markers (CD44, KCNJ10, and TGFBR2) were upregulated under hyperglycaemia in the NGS dataset." (PMID 41419458, 2025).
brain tumors (4 papers, 2007 to 2024). "This analysis identified neoplasms and nervous system diseases as the most associated diseases with the TRPV2 interactome, and highlighted a set of genes previously associated to brain neoplasms, such as: ABR, FGF1, KCNJ10, PEBP1, PLP1, SDC3 and TRPV2." (PMID 29719613, 2018).
Myokymia (4 papers, 2015 to 2023). Myokymia consists of involuntary, fine, continuous, undulating contractions that spread across the affected striated muscle. "Dogs with isolated, myokymia and neuromyotonia were significantly older at presentation (average 4.9 years versus 0.9 years), compared to dogs biallelic for the KCNJ10 variant, and the onset of signs appeared later in life (average of 23 months versus 6 months)." (PMID 37905444, 2023). "Information on the breed, clinical phenotype (spinocerebellar‐like ataxia and myokymia/neuromyotonia) and genotype (KCNJ10 and CAPN1) of the 33 investigated dogs." (PMID 37905444, 2023). "The etiology of myokymia/neuromyotonia in these dogs is unclear and their possible association with KCNJ10 variants has not been investigated." (PMID 37905444, 2023). "Neither myokymia nor neuromyotonia is reported in association with KCNJ10 or CAPN1 variants in humans or in experimental animal models." (PMID 37905444, 2023). "Thus, three of the ataxic Jack Russell Terriers and the Danish-Swedish-Farm Dog with neuromyotonia, myokymia and facial rubbing were homozygous for the wild-type alleles at both CAPN1:c.344G>A and KCNJ10:c.627C>G." (PMID 25998802, 2015). "Moreover, no KCNJ10 variant has yet been found in dogs with myokymia and neuromyotonia without SCA, suggesting that another variant (that has not been described yet) is probably associated with myokymia and neuromyotonia." (PMID 37341581, 2023). "Delay and/or absence of central BAEP waves (described in detail in9, 26) were found in all dogs biallelic for the KCNJ10 variant, but not in the Parson Russell terrier biallelic for the CAPN1 variant, nor in a dog with myokymia/neuromyotonia alone." (PMID 37905444, 2023). "In dogs, variants in KCNJ10 seem to be highly associated with SCA and not with myokymia and neuromyotonia, as all dogs homozygous for a KCNJ10 variant have SCA but not all of them have myokymia and neuromyotonia." (PMID 37341581, 2023).
generalized epilepsy (3 papers, 2007 to 2017). Epilepsy that is characterized by generalized seizure types and may have typical interictal and/or ictal EEG findings that accompany generalized seizure types (for example generalized spike-wave). "We found that some KCNJ10 tagSNPs were associated with the susceptibility and efficacy of genetic generalized epilepsy." (PMID 25874548, 2015). "In our studies, we performed a gene-wide tagging study of the association between KCNJ10 tagSNPs and the susceptibility/AEDs efficacy of genetic generalized epilepsy in Chinese population." (PMID 25874548, 2015). "Some studies found that KCNJ10 gene rs1130183 (Arg271Cys) was associated with seizure resistance in groups of patients with both focal and generalized epilepsy.It is also suggested that a missense variant (Thr262Ser) in KCNJ10 was likely to be candidate gene for seizure." (PMID 25874548, 2015). "However, KCNJ10 rs1130183 dose not contribute to risk of seizure susceptibility in Turkish or Indian patients with idiopathic generalized epilepsies." (PMID 25874548, 2015).
Hypocalciuria (3 papers, 2018 to 2021). An abnormally decreased calcium concentration in the urine. "Loss-of-function mutations in the KCNJ10 gene encoding Kir4.1 subunit result in EAST/SeSAME syndrome, a complex electrolyte imbalance disorder manifested as hypotension, natriuresis, hypocalciuria, hypomagnesemia, and hypokalemic metabolic alkalosis." (PMID 33524393, 2021).
neuropathy (3 papers, 2021 to 2024). A disorder affecting the nervous system that manifests with pain, tingling, numbness, and/or muscle weakness. "We postulate that dysregulation of GPR37L1/KCNJ10 signaling in SGCs in neuropathy conditions (CIPN and DPN) will impair the SGC’s function of K+ buffering, leading to sequential increases in extracellular levels of K+, nociceptor excitability, and pain sensitivity." (PMID 38530364, 2024). "Dead M. leprae increased the expression of WNK, IFNB, IKBKA, and HLA-DQA1 (genes related to neuropathy), in addition to GJA1 and RAF1 (for Schwann cell reprogramming) and KCNJ10, OLIG1, SHH, and SOSTDC1 (for neural regeneration)." (PMID 35492305, 2022).
sensorineural deafness (3 papers, 2013 to 2021). "Biallelic mutations in KCNJ10 cause sensorineural hearing loss as part of a rare and complex syndrome, called EAST/SeSAME syndrome, consisting of epilepsy, ataxia, sensorineural deafness, and renal tubulopathy (OMIM #612780)." (PMID 34562878, 2021).
Anxiety (2 papers, 2025). Intense feelings of nervousness, tension, or panic often arise in response to interpersonal stresses. "Qrr1 also shows strong concordance with the orthologous human Chr1 q21–q23 interval, which harbors genes such as Rgs2 (anxiety), Apoa2 (atherosclerosis), and Kcnj10 (seizure susceptibility)." (PMID 41225772, 2025).
hereditary ataxia (2 papers, 2015 to 2016). An instance of an atactic disorder that is caused by an inherited genomic modification in an individual. "In order to identify further mutations associated with hereditary ataxia explaining the cases with the homozygous KCNJ10 C/C genotype, exon 2 and 3 of KCNJ10 with their exon/intron or exon/UTR boundaries were sequenced in PRT and JRT." (PMID 27724896, 2016). "In the present study, 16/21 cases of hereditary ataxia perfectly co-segregated with the KCNJ10:c.627C > G mutation." (PMID 27724896, 2016). "Three Smooth-Haired Fox Terriers with hereditary ataxia and two Toy Fox Terriers with a similar phenotype were all homozygous for the KCNJ10 mutation." (PMID 25998802, 2015). "Our data confirmed the presence of the KCNJ10:c.627C > G mutation in PRT and JRT affected with hereditary ataxia." (PMID 27724896, 2016). "In conclusion, a few but not all cases of hereditary ataxia being heterozygous or homozygous for the wild-type allele of KCNJ10 could be explained by the KCNJ10:g.22141027insC mutation." (PMID 27724896, 2016). "However, some cases of hereditary ataxia could not be explained through the KCNJ10:c.627C > G nor the CAPN1:c.344G > A mutation." (PMID 27724896, 2016). "Genetic testing using the KCNJ10:c.627C > G and the CAPN1:c.344G > A mutations deems not to be sufficient to capture all cases of hereditary ataxia in PRT and JRT." (PMID 27724896, 2016). "In agreement with a previous study, one histopathologically confirmed case of hereditary ataxia and two clinically affected cases carried neither the CAPN1:c.344G > A allele nor the homozygous KCNJ10:c.627C > G genotype." (PMID 27724896, 2016).
asthma (1 paper, 2025). "Our top hits KCNJ10 and FERMT1 also showed association with asthma." (PMID 40410506, 2025).
Becker muscular dystrophies (1 paper, 2016). "While KCNJ10 and SLC6A3 codify for ion channels and thus their contribution to epileptogenesis is not unexpected, DMD codes for dystrophin, which has been traditionally associated with X-linked Duchenne and Becker muscular dystrophies." (PMID 27984588, 2016).
breast carcinoma (1 paper, 2022). "Survival analysis of ion channels interacting with EMT-related genes showed KCNN4 (p-value: 0.071), CFTR (p-value: 0.16), KCNJ10 (p-value: 0.17), VDAC1 (p-value: 0.000003) and VDAC2 (p-value: 0.052) the level of expression associated with survival of breast cancer patients." (PMID 35326596, 2022).
conductive hearing loss (1 paper, 2014). "Among the 96 inpatients with conductive hearing loss, we detected KCNJ10 heterozygous c.812G>A in four cases (4/96, 4.2%), heterozygous c.811C>T in one case (1/96, 1.0%), and heterozygous c.1042C>T in one case (1/96, 1.0%)." (PMID 25372295, 2014). "In addition, we screened KCNJ10 in patients diagnosed with conductive hearing loss having non-EVA inner ear malformations." (PMID 25372295, 2014). "No statistical difference in the KCNJ10 c.812G>A and c.1042C>T mutations was observed between the normal-hearing group and the NSEVA cases with zero, one, or two mutations in SLC26A4, patients with inner ear malformation, or patients with conductive hearing loss (χ2 = 6.287, P = 0.179)." (PMID 25372295, 2014).
cone dystrophy (1 paper, 2012). An inherited ocular disorder characterized by the loss of cone cells, the photoreceptors responsible for both central and color vision. "However, these patients did not develop a cone dystrophy, since mutations in KCNJ10 primarily affect the Müller cell functions, while mutations in KCNV2 lead to disturbed functional integrity of the photoreceptors and probably impair their postreceptoral signaling." (PMID 23077521, 2012).
enlarged vestibular aqueduct syndrome (1 paper, 2011). "In patients with enlarged vestibular aqueduct syndrome, both single heterozygous genes SLC26A4 (MIM*605646) and KCNJ10 (MIM*602208) induced the hearing loss in these patients." (PMID 21935370, 2011).
leprosy (1 paper, 2022). Leprosy is a chronic infectious disease affecting primarily the skin and peripheral nervous system. "SHH, WNK, and KCNJ10 were upregulated in leprosy nerve biopsies and in dead M. leprae-infected Schwann cells." (PMID 35492305, 2022).
pancreatic cancer (1 paper, 2023). "In the current study, a total of 17 genes with prognostic values have been identified, of which 8 genes (SFXN5, LRRC8E, KCNJ10, UPB1, SLC43A2, SLC38A10, ACCS, and SLC38A5) were identified for the first time in pancreatic cancer." (PMID 37333498, 2023).
Retinal atrophy (1 paper, 2018). A nonspecific term denoting wasting, especially as a result of degeneration, of the retinal pigment epithelium (RPE) and neurosensory retinal cells. "In summary, permanent loss-of-Kcnj10 function in OLs results in visual dysfunction with retinal atrophy in adult mice as well as motor deficits and early mortality." (PMID 30204081, 2018).
neurological disorders (16 papers, 2012 to 2025). "Twenty four of the 28 dogs with neurologic disease were homozygous for the mutant KCNJ10:c.627G allele." (PMID 25998802, 2015). "More recently a missense mutation in the KCNJ10 gene [GenBank: XM_545752.3] was found to be significantly associated with a similar neurological disease in 14 ataxic dogs belonging to the Russell group of terriers." (PMID 25998802, 2015).
neurodegenerative disease (5 papers, 2020 to 2024). A disorder of the central nervous system characterized by gradual and progressive loss of neural tissue and neurologic function. "DNA methylation levels of the Kir4.1 gene, KCNJ10, were negatively correlated with Kir4.1 expression in astrocytes, which implies that epigenetic regulation of Kir4.1 might be a possible therapeutic direction for neurodegenerative diseases associated with Kir4.1 channels, including AD." (PMID 35222082, 2022).
cancer (3 papers, 2017 to 2025). A tumor composed of atypical neoplastic, often pleomorphic cells that invade other tissues. "Based on the single‐cell sequencing derived from NPC clinical samples, RANBP17 is expressed in EBV‐associated NPC cells, KCNJ10 is detectable in myeloid cells, and CXCR5 is dormantly expressed by B cells, while cancer‐associated fibroblasts mainly express CCL19 and CCL21." (PMID 41397929, 2025).
peripheral neuropathy (2 papers, 2024). A disorder affecting the peripheral nervous system. "Remarkably, MaR1 conferred protection against chemotherapy-induced peripheral neuropathy (CIPN) by inducing GPR37L1-dependent upregulation of surface KCNJ10 expression and KCNJ10-mediated K+ currents in SGCs." (PMID 38530364, 2024).
KCNJ10 also shares sentences with these, for which no sentence is quoted: electrolyte imbalance (18 papers); autism (12); diabetes (11); ischemia (7); tumor (7); Gitelman syndrome (6); Alzheimer disease (5); Cognitive impairment (5); neurodevelopmental disorder (5); Rett syndrome (5); Hypomagnesemia (4); status epilepticus (4); Stroke (4); Alkalosis (3); cerebellar ataxia (3); Channelopathies (3); Gliosis (3); Hearing impairment (3); movement disorder (3); neuromyotonia (3); Parkinson disease (3); absence seizures (2); Autoimmunity (2); autosomal dominant lateral temporal lobe epilepsy (2); Bartter syndrome type 3 (2); Cerebral ischemia (2); demyelination (2); developmental delay (2); diabetic retinopathy (2); epilepsy syndrome (2).
A further 82 diseases each share a sentence with KCNJ10 in 2 papers or fewer.